SAXO1 (stabilizer of axonemal microtubules 1)
Description:
May play a role in the regulation of cilium length. Stabilizes microtubules at low temperature.
Synonyms: C9orf138; FAM154A; MGC35182
Tractability: No criterion of Open Targets' tractability assessment is met for any kind of drug.
Gene: Protein-coding gene on chromosome 9 (18,858,906 to 19,049,358, reverse strand). Ensembl gene ENSG00000155875.
Subcellular location: Cytoplasm, cytoskeleton, microtubule organizing center, centrosome, centriole; Cytoplasm, cytoskeleton, cilium basal body; Cytoplasm, cytoskeleton, cilium axoneme; Cytoplasm, cytoskeleton, microtubule organizing center, centrosome; Cytoplasm, cytoskeleton, flagellum axoneme
Subcellular location (Human Protein Atlas): End piece; Flagellar centriole; Mid piece
Gene Ontology:
Molecular function: microtubule binding; protein binding
Biological process: cellular response to cold; cold acclimation; positive regulation of cilium assembly; protein stabilization
Cellular component: axonemal microtubule; centriole; ciliary basal body; motile cilium; sperm end piece; sperm flagellum; sperm midpiece; cytoskeleton; axoneme; centrosome
Genetic constraint (gnomAD): Loss-of-function variants: 20 observed, 19.05 expected, observed/expected ratio (o/e) 1.05, 90% interval 0.74 to 1.52. The upper end of that interval is the gene's LOEUF score, 1.52, which puts it in group 6 of 6, group 1 being the genes least tolerant of losing a copy. Missense variants: 825 observed, 611.41 expected, observed/expected ratio (o/e) 1.35, 90% interval 1.27 to 1.43. Synonymous variants: 268 observed, 223.91 expected, observed/expected ratio (o/e) 1.2, 90% interval 1.08 to 1.32.
Homologues: Orthologues: chimpanzee SAXO1 (99% identical), macaque SAXO1 (94% identical), rabbit SAXO1 (85% identical), dog SAXO1 (83% identical), pig SAXO1 (81% identical), mouse Saxo1 (66% identical), rat Saxo1 (66% identical), mouse Gm15229 (60% identical), Caenorhabditis elegans T08G11.3 (23% identical), Caenorhabditis elegans H03A11.2 (20% identical), Drosophila melanogaster CG7131 (19% identical), Caenorhabditis elegans H13N06.7 (10% identical). Paralogues in human: SAXO2 (33% identical).
Diseases named in the same sentence as SAXO1 in open-access papers:
SAXO1 is named in the same sentence as 3 diseases in open-access papers, as found by Europe PMC text mining. Sharing a sentence is not in itself a finding about the gene and the disease. The quoted sentences say what the papers report.
infection (1 paper, 2022). The state of being infected such as from the introduction of a foreign agent such as serum, vaccine, antigenic substance or organism. "In cecum, seven upregulated genes were found in common (Gbp10, Serpina1, Ifng, Saxo1, Ighv1-59, Ighv1-63, Igkv4-79) in the infection vs. control comparisons." (PMID 36704785, 2022).
SAXO1 also shares sentences with these, for which no sentence is quoted: asthenozoospermia (1 paper); synucleinopathy (1).